LINC01589 (long independently transcribed non-coding RNA 1589)
Synonyms: CTA-941F9.9; TCONS_00029353
Gene: Long non-coding RNA gene on chromosome 22 (45,604,413 to 45,639,173, reverse strand). Ensembl gene ENSG00000238120.
Diseases named in the same sentence as LINC01589 in open-access papers:
LINC01589 is named in the same sentence as 3 diseases in open-access papers, as found by Europe PMC text mining. Sharing a sentence is not in itself a finding about the gene and the disease. The quoted sentences say what the papers report.
pancreatic ductal adenocarcinoma (1 paper, 2020). An infiltrating adenocarcinoma that arises from the epithelial cells of the pancreas. "In addition, in pancreatic ductal adenocarcinoma cells, LINC01589 expression is significantly increased, and LINC01589 expression is closely associated with OS in patients with this malignancy." (PMID 33175697, 2020).
LINC01589 also shares sentences with these, for which no sentence is quoted: endometrial cancer (1 paper); tumor (1).